GATA3 (GATA binding protein 3)
Diseases named in the same sentence as GATA3 in open-access papers (continued):
Sharing a sentence is not in itself a finding about the gene and the disease.
asthma (continued). "Furthermore, inflammatory pathology is supported by the presence of GATA3 and STAT6 in asthma and inflammatory gene clusters in the pathway analysis." (PMID 35386986, 2021). "Exposure to OVA resulted in the upregulation of GATA-3 and RORγt protein expression and downregulation of Foxp3 expression in mice, suggesting that OVA might induce asthma through the GATA-3, RORγt, and Foxp3 signaling pathways." (PMID 33806085, 2021). "Furthermore, cell suspensions from the lung were stained with antibodies specific for CD4 and the master transcription factors for T-bet, Gata-3, RORγt, and Foxp3 to better understand the roles of CD4+ T subsets in the pathogenesis of asthma." (PMID 29162668, 2017). "Huai Qi Huang could also regulate Th1/Th2 and Treg/Th17 via the re-balance of cytokine profiles and ratios of transcription factors, T-bet/Gata-3 and Foxp3/RORγt in OVA-induced asthma model mice." (PMID 29162668, 2017). "Therefore, we summarized the miRNAs involved in the pathways common to AR and asthma, such as IL-13, GATA binding protein 3 (GATA-3), and mucin secretion, which have been discovered either in asthma or in the study of AR." (PMID 27187364, 2016). "Furthermore, GATA-3 expression in fresh samples was correlated with FEV1 reversibility, a main feature of asthma." (PMID 22768198, 2012). "Furthermore, when a correlation test was applied between transcription factors and major clinical characteristics, the strongest correlations were found between GATA-3 and FEV1 reversibility, a key characteristic of asthma." (PMID 22768198, 2012). "As a result, they could be bonded asthma-related proteins, such as AR, FOXA1, GATA3, and GATA6." (PMID 37569643, 2023). "Inhibition of GATA-3 is possible by using DNA molecules that bind specific GATA-3 sequences, an example of which is SB010, administered by inhalation, that has been already tested in eosinophilic chronic obstructive pulmonary disease and asthma and promising results have been reported." (PMID 36291990, 2022). "However, silencing/OE of MBD2 in severe asthma+ DHT group did not significantly change the GATA3 detection within the group." (PMID 36062195, 2022). "Hi-C data in hematopoietic cells showed that two proxies of rs2589561 (r2 > 0.9) are located in a region that interacts with the GATA3 promoter in CD4+ T cells, suggesting that rs2589561 could function as a distal regulator of GATA3 in this asthma relevant cell type." (PMID 34669738, 2021). "However, the Th1 master transcription factor T-bet and the Th2 master transcription factor Gata3 were comparable in CD4+ T cells from both control and asthma mice, suggesting that Th2 differentiation in asthma may be independent of Gata3." (PMID 31231429, 2019). "Since GATA3 and FOXP3 are the principal transcription factors of Th2 and Treg cells, respectively, GATA3/FOXP3 mRNA expression ratio may be considered as a useful substitute parameter to determine Th2/Treg cells status in patients with asthma." (PMID 30116273, 2018). "In conclusion, elevated serum levels of IL-4 and increased expression of GATA3 and GATA3/FOXP3 ratio in PBMCs isolated from patients with asthma indicate an imbalance in the levels of Th2/Treg-related transcription factors and a Th2-deviated pattern in patients with asthma." (PMID 30116273, 2018). "RORγt, the key transcriptional regulator of Th17 cells, was highly expressed in the neutrophils-dominant asthma group compared to the conventional asthma group, whereas GATA3, the key transcriptional regulator of Th2 cells, was not overtly different between the two groups." (PMID 30150897, 2018). "These increases of IL-23, MIP-2 and GATA3 were significantly declined in rMS-Ag85a-IL-17a vaccinated group; however, the administration of rMS-Ag85a-IL-17a did not affect RORγt expression in severe asthma." (PMID 26974537, 2016).
asthma (continued). "Following 48 h of incubation in medium containing SOCS3 siRNA or NT siRNA, the analysis revealed a reduced transcription of GATA3 in eosinophils from patients with asthma (n = 5) treated with SOCS3 siRNA, but not in those incubated with the negative control (p < 0.05)." (PMID 25764157, 2015). "Although the precise effects of T-bet and GATA-3 in the pathogenesis of airway remodeling in asthma are still not fully understood, our finding of underexpression of GATA-3 in the airways asthma model mice suggests that HPN has a significant inhibitory role in asthma." (PMID 21772663, 2011). "While not a direct report of GATA-3 findings, it emphasizes the integration of comprehensive metabolic profiling—including insulin sensitivity and body composition—alongside traditional inflammatory and respiratory metrics in randomized controlled asthma trials." (PMID 41567689, 2026). "Since the transcription factor GATA-3 is essential for TH2 cell development and the production of several TH2 type cytokines this intracellular molecule represents a new promising target for therapeutic intervention in asthma that might even effect airway remodelling." (PMID 18315835, 2008). "A significant decrease in the expression of the Th1 polarization factor IFN-γ and a significant increase in the expression of the Th2 polarization factors IL-4 and GATA-3 in Spp1−/−+OVA mice, which suggests a lack of OPN, increases the Th2-polarized environment in asthma." (PMID 40401951, 2025). "However, simple exposure to 1 μg LPS without asthma induction (LPS/PBS) did not significantly affect Foxp3, GATA3, or ROR-γt mRNA levels nor IL-10, TGF-β, IL-4, IL-5, IL-13, or IL-17 levels (p > 0.05) compared to those of Control mice." (PMID 33072079, 2020).
breast tumors (92 papers, 2006 to 2025). "GATA-3 is associated with luminal cell differentiation in mammary glands, and the majority of human breast tumors originate from epithelial luminal cells." (PMID 37483298, 2023). "The established GATA3 mutant cell lines still express wild-type GATA3, which mimics the situation in breast tumors since most of the GATA3 mutations found in patients are heterozygous." (PMID 35154280, 2022). "In breast tumors and cell lines, expression of GATA3 is strongly associated with those of ESR1 and FOXA1." (PMID 34831189, 2021). "GATA3 protein expression is a favourable prognostic indicator in ER-positive breast tumours, and numerous studies have reported that loss of GATA3 expression is associated with poor prognosis and propensity for tumour metastasis." (PMID 33298139, 2020). "This analysis revealed that her metachronous bilateral breast tumors had the same GATA3 and CSMD1 mutations." (PMID 32833091, 2020). "In one study, GATA3 expression was found to be associated with favorable outcome in all the breast tumors in the study, while the association was lost when only ER positive cancers were analyzed." (PMID 31718619, 2019). "A novel classification scheme defines distinct clinical features for patients bearing breast tumors with mutations in the second GATA3 zinc-finger (ZnFn2)." (PMID 29535312, 2018). "Systems-level analyses have identified GATA3 as one of the most frequently mutated genes in breast cancers, yet the function of GATA3 mutations in breast tumors is poorly understood." (PMID 29535312, 2018). "Based on the The Cancer Genome Atlas (TCGA) data cohort, approximately 10% of breast tumors harbor somatic mutations in the GATA3 gene." (PMID 29535312, 2018). "GATA3 is one of a few most frequently mutated genes in human breast tumors, and the majority of GATA3 mutations result in frameshift and loss of normal GATA3 function." (PMID 27374105, 2016). "GATA3 expression was associated with 829 breast tumor-specific enhancer probes located on many different chromosomes." (PMID 27833659, 2016). "However, the role of GATA3 somatic mutations in the development of breast tumor characteristics, patient survival outcomes, and its impact on tumor gene expression profiles is poorly understood." (PMID 33462316, 2021). "Analysis of six different heterozygous GATA3 mutations from eight breast tumors has demonstrated loss or reduction of DNA binding ability, aberrant nuclear localization, decrease in transcription activation, and alterations in invasiveness, but not proliferation." (PMID 24758297, 2014). "GATA3 was recently shown to be somatically mutated in some ER+ breast tumors." (PMID 19638211, 2009). "In this case, high expression of GATA3 and ER supported the diagnosis of metastasis from the known breast tumor." (PMID 41018463, 2025). "GCDFP-15, mammaglobin, and GATA3 are relatively specific breast tumor markers, while ER/PR are also expressed." (PMID 41018463, 2025). "When we evaluated which immune-associated genes were differentially expressed between HR + HER2- and TN breast tumors within the immune-high cluster, GATA3 (logFC = 3.8; adj." (PMID 39149486, 2024). "Immunohistochemical staining of breast tumors confirms co-expression between GATA3 and P4HTM at the protein level." (PMID 36909571, 2023). "Primary breast tumors have more specific markers, such as GATA3 and GCDFP-15, and the former has a higher positive rate and is more meaningful in differentiating tumors from other sites, which is consistent with the results of previous studies." (PMID 37337182, 2023). "Luminal tumors were named due to their gene expression similarities to luminal breast tumors and positivity for markers of differentiated urothelium like GATA3, and the uroplakins." (PMID 36737799, 2023).
breast tumors (continued). "NOD/SCID mice were inoculated subcutaneously with GATA3 p.D335Gfs mutant breast tumor chunks (2–3 mm) for tumor development." (PMID 35440675, 2022). "The top eight genes that negatively correlated to POLR3G expression (MLPH, FOXA1, SPDEF, AR, SIDT1, AGRP2, XBP1, GATA3) are typically overexpressed in ER+ breast tumors as compared to ER- breast tumors." (PMID 36497214, 2022). "The transcription factor GATA3 is overexpressed in lower grade breast tumors with a better prognosis, while its low levels are correlated with larger tumors." (PMID 36078127, 2022). "CREBBP, EP300, ESR1, GATA3, and MYC are well-known genetic biomarkers and mutate frequently in breast tumors." (PMID 34235216, 2021). "GATA3 is also amplified in breast tumors, mostly in ER-negative tumors where amplification correlates with decreased rather than increased GATA3 expression, suggesting the existence of different driver genes in this 10p14 amplicon." (PMID 34831189, 2021). "Both GATA3 and GREB1 have been linked to estrogen receptor-positive breast tumors and have been proposed as markers for patient response to hormone treatment." (PMID 32605588, 2020). "GATA3 is a known breast tumor suppressor and an important marker of urothelial differentiation which is involved in the prevention of bladder cancer progression." (PMID 31779626, 2019). "GATA3, ZNF703, and MAP3K1 are in the group 1 genes associated with acquired endocrine therapy resistance in breast tumors expressing ESR1 and ERBB2." (PMID 29738475, 2018). "Deleterious mutations in GATA3, an activating SF3B1 mutation (K700E), and an activating AKT1 mutation (E17K) were observed in eight (16.7%), three (6.3%), and three (6.3%) breast tumors, respectively." (PMID 29464067, 2018). "Consistent with the previous literature, breast tumors with lower GATA3 expression showed significantly worse prognosis than tumors with higher GATA3 expression." (PMID 29535312, 2018). "Mouse studies have shown that Gata3 is critical for breast development and that GATA3 gene dosage affects breast tumor progression." (PMID 29262572, 2017). "This is the case of GATA3 in breast tumors, ZNF292 in low grade gliomas, ARID5B in uterine carcinomas, and MYC in diffuse B-cell lymphomas." (PMID 26792175, 2016). "Specifically, all three over-expressed key regulators in breast tumors, GATA3, E2F1 and RAD21, showed connection with these two lincRNAs." (PMID 27897201, 2016). "We previously examined the expression of mRNAs between cellular subsets of the developing mammary gland, found GATA-3 to be specifically expressed in epithelial cells and went on to identify GATA-3 as an important breast tumour suppressor gene." (PMID 26070602, 2015). "The transcription factor GATA3 is a favorable prognostic indicator in estrogen receptor-α (ERα)-positive breast tumors in which it participates with ERα and FOXA1 in a complex transcriptional regulatory program driving tumor growth." (PMID 24758297, 2014). "In contrast to GATA3 and FOXA1, the ZNF217 gene is amplified at 20q13 in ~20% of breast tumors and is associated with aggressive breast disease." (PMID 24962896, 2014). "GATA3 is expressed in normal mammary epithelial luminal progenitor cells and in the luminal A molecular subtype (ER and/or PR positive tumors) of human breast tumors." (PMID 22022496, 2011). "The immunohistochemical evaluation of FOXA1 and GATA-3 in breast tumour samples revealed that in 201 of interpretable cases a very significant direct association between the expression of FOXA1 and GATA-3 was observed (P < 0.0001)." (PMID 19549328, 2009). "Meta-analysis of four microarray datasets indicated that GATA-3 was a strong predictor of clinical outcome in breast tumours and is among the best predictors of ER-positive status." (PMID 19549328, 2009).
breast tumors (continued). "Several studies have shown that FOXA1 and GATA-3 expression are strong predictors of better clinical outcome in breast tumours and are among the best predictors of ERα-positive status." (PMID 19549328, 2009). "GATA3, known as a marker used to identify mammary or urothelial origin of metastases from unknown primary tumors, is widely expressed in breast tumors and has been suggested as a potential prognostic and/or treatment predictive biomarker." (PMID 39242600, 2024). "Indeed, similar results have been reported in human male breast tumors, whereby GATA-3 was less frequently expressed and uncorrelated with hormone receptors (ER/PR), distant metastases, or survival rate." (PMID 37483298, 2023). "Among them, GATA3 is a key transcription factor involved in the development of breast tumors." (PMID 37996875, 2023). "The predictive potential of GATA-3 in women with breast tumors has been explored." (PMID 37483298, 2023). "We found that GATA3 mRNA was highly correlated with breast tumor intrinsic subtypes." (PMID 34976209, 2022). "A study indicated that CAFs in GATA3+ breast tumours could produce TSLP+ DCs, which exist in tumour-draining lymph nodes but not in nondraining lymph nodes." (PMID 35936012, 2022). "GATA3 takes a crucial role in normal mammary gland development, and its expression demonstrates high correlation with the estrogen receptor α (ERa) in human breast tumors." (PMID 33907495, 2021). "Interestingly, a substantial inverse expression correlation was detected between circ_0044234 and miR-135b-5p as well as between miR-135b-5p and GATA3 in breast tumors." (PMID 34126989, 2021). "Likewise, in human breast tumors, low GATA3 expression was shown to be a strong predictor of poor clinical outcome, high tumor grade, positive lymph node status, and large tumor size." (PMID 32225066, 2020). "In addition, GATA3 expression was strongly correlated with the luminal A subtype of breast tumors, which carried the best prognostic outcome for human patients." (PMID 32225066, 2020). "These subtypes are known to have poor clinical outcomes, which indicates that GATA3 expression may be greatly involved in breast tumor malignancy." (PMID 30872657, 2019). "GATA3 is positively associated with ESR1, while TRPS1 is correlated with ERBB2 and might act as a potential modulator of chemosensitivity in breast tumor." (PMID 28423734, 2017). "For example, we found that hundreds of tumor-specific enhancers are linked to GATA3 overexpression in non-basal breast tumors." (PMID 27833659, 2016). "For example, we identified GATA3 and FOXA1 as highly linked TFs in breast tumors." (PMID 27833659, 2016). "Therefore, two breast tumors with mutation and amplification respectively in the same gene, such as in PIK3CA or GATA3, yield two distinct tumors of low and high grade, respectively." (PMID 27283966, 2016). "Finally, we have also shown that GATA3 downregulation is required for progestin-induced in vitro cell proliferation and in vivo breast tumor growth." (PMID 25479686, 2014). "It was also demonstrated that miR-30c was transcriptionally regulated by GATA3 in breast tumors." (PMID 24748983, 2014). "Tumor gene expression profiles (NKI-147) were processed in the same fashion as the sorted cell lines and tumor profiles were compared to the ESR1, GATA3, and c-Myb gene signatures to demonstrate which breast tumor subtypes were enriched for these signatures (left)." (PMID 20949095, 2010). "Furthermore, in a meta-analysis of ERα 10 genes were proposed as classifier of ERα positive breast tumours, listing GATA3 as one of these." (PMID 18533032, 2008). "GATA3 levels are also considered a good prognostic biomarker in breast tumours." (PMID 18533032, 2008). "In aggressive breast tumours where GATA3 is not expressed and not mutated, a new targeted therapy based on demethylation of the promoter region of GATA3 could be considered." (PMID 40585280, 2025).